SNRNP25 (small nuclear ribonucleoprotein U11/U12 subunit 25)
Synonyms: U11/U12-25K; C16orf33
Gene: Protein-coding gene on chromosome 16 (53,828 to 57,669, forward strand). Ensembl gene ENSG00000161981.
Subcellular location: Nucleus
Subcellular location (Human Protein Atlas): Nucleoplasm; Cytokinetic bridge; Cytosol
Pathways (Reactome):
Metabolism of RNA: mRNA Splicing - Minor Pathway
Genetic constraint (gnomAD): Loss-of-function variants: 21 observed, 23.95 expected, observed/expected ratio (o/e) 0.88, 90% interval 0.62 to 1.26. The upper end of that interval is the gene's LOEUF score, 1.26, which puts it in group 5 of 6, group 1 being the genes least tolerant of losing a copy. Missense variants: 160 observed, 162.8 expected, observed/expected ratio (o/e) 0.98, 90% interval 0.86 to 1.12. Synonymous variants: 63 observed, 60.58 expected, observed/expected ratio (o/e) 1.04, 90% interval 0.85 to 1.28.
Homologues: Orthologues: chimpanzee SNRNP25 (100% identical), guinea pig SNRNP25 (98% identical), mouse Snrnp25 (98% identical), rat Snrnp25 (98% identical), rabbit SNRNP25 (98% identical), dog SNRNP25 (97% identical), pig SNRNP25 (95% identical), tropical clawed frog snrnp25 (80% identical), zebrafish snrnp25 (80% identical).
Diseases named in the same sentence as SNRNP25 in open-access papers:
SNRNP25 is named in the same sentence as 13 diseases in open-access papers, as found by Europe PMC text mining. Sharing a sentence is not in itself a finding about the gene and the disease. The quoted sentences say what the papers report.
osteosarcoma (4 papers, 2014 to 2024). A usually aggressive malignant bone-forming mesenchymal neoplasm, predominantly affecting adolescents and young adults. "The LRP1–SNRNP25, LRP1, SNRNP25, or empty vector was transfected into osteosarcoma cells with Lipo3000, and the cells were cultured for 48 h." (PMID 38678020, 2024). "First, we constructed SAOS2 and 143B osteosarcoma cell lines that stably overexpressed LRP1–SNRNP25, LRP1, SNRNP25, or the corresponding empty vector." (PMID 38678020, 2024). "LRP1-SNRNP25 expression was increased in both tumors via the LRP1 promoter activity of the fusion gene compared to the wild-type SNRNP25 expression in other osteosarcomas specimen." (PMID 26617523, 2015). "The FISH also revealed amplification of both LRP1 and SNRNP25, suggesting a complex genetic alteration of osteosarcoma." (PMID 25300797, 2014). "We sought to detect chimeric KCNMB4-CCND3 and LRP1-SNRNP25 protein products in 31 human osteosarcoma tissues by western blotting with antibodies against CCND3, KCNMB4, SNRNP25 and LRP1." (PMID 25300797, 2014).
SNRNP25 also shares sentences with these, for which no sentence is quoted: tumor (2 papers); bone sarcoma (1); cancer (1); chondrosarcoma (1); liposarcoma (1); malignant fibrous histiocytoma (1); malignant peripheral nerve sheath tumor (1); rhabdomyosarcoma (1); sarcoma (1); small cell osteosarcoma (1); synovial sarcoma (1); undifferentiated pleomorphic sarcoma (1).